AACS (acetoacetyl-CoA synthetase)
Description:
Converts acetoacetate to acetoacetyl-CoA in the cytosol (By similarity). Ketone body-utilizing enzyme, responsible for the synthesis of cholesterol and fatty acids (By similarity).
Synonyms: ACSF1; FLJ12389; SUR-5
Tractability: PROTAC: ubiquitination databases record sites on it; its protein half-life has been measured.
Gene: Protein-coding gene on chromosome 12 (125,065,364 to 125,143,333, forward strand). Ensembl gene ENSG00000081760.
Subcellular location: Cytoplasm, cytosol
Subcellular location (Human Protein Atlas): Vesicles
Pathways (Reactome):
Metabolism: Synthesis of Ketone Bodies
Gene Ontology:
Molecular function: protein binding; acetoacetate-CoA ligase activity
Biological process: ketone body biosynthetic process; positive regulation of insulin secretion; lipid metabolic process
Cellular component: cytosol
Genetic constraint (gnomAD): Loss-of-function variants: 65 observed, 82.61 expected, observed/expected ratio (o/e) 0.79, 90% interval 0.64 to 0.97. The upper end of that interval is the gene's LOEUF score, 0.97, which puts it in group 4 of 6, group 1 being the genes least tolerant of losing a copy. Missense variants: 858 observed, 897.7 expected, observed/expected ratio (o/e) 0.96, 90% interval 0.9 to 1.01. Synonymous variants: 333 observed, 349.63 expected, observed/expected ratio (o/e) 0.95, 90% interval 0.87 to 1.04.
Homologues: Orthologues: chimpanzee AACS (99% identical), macaque AACS (98% identical), pig AACS (91% identical), mouse Aacs (90% identical), rat Aacs (89% identical), guinea pig AACS (86% identical), zebrafish aacs (78% identical), tropical clawed frog aacs (78% identical), rabbit AACS (64% identical), Caenorhabditis elegans sur-5 (39% identical). Paralogues in human: ACSS2 (24% identical), ACSS1 (23% identical), ACSS3 (19% identical), ACSM2B (19% identical), ACSM4 (19% identical), ACSM2A (18% identical), ACSM5 (17% identical), ACSM3 (17% identical), ACSM1 (16% identical), ACSF2 (15% identical), ACSF3 (12% identical), ACSM6 (12% identical), and 1 more.
Diseases named in the same sentence as AACS in open-access papers:
AACS is named in the same sentence as 17 diseases in open-access papers, as found by Europe PMC text mining. Sharing a sentence is not in itself a finding about the gene and the disease. The quoted sentences say what the papers report.
Obesity (6 papers, 2014 to 2023). Accumulation of substantial excess body fat. "In obesity, AACS was highly expressed in the differentiated osteoclasts, but did not in osteoblast differentiation." (PMID 38075675, 2023). "Obesity was also found to affect expression of rat AACS mRNA in skeletal muscle." (PMID 37356666, 2023). "Moreover, high-fat diet (HFD)-induced obesity determines the increases of the acetoacetyl-CoA synthetase (AACS) gene expression, involved in utilizing KBs for the fatty acid-synthesis during adipose tissue development." (PMID 33406758, 2021). "We observed that the addition of cDDGS positively affects the expression of several genes that have been recently proposed as potential targets for the treatment of obesity, diabetes, cardiovascular disease, and Alzheimer’s disease (e.g., FASN, AACS, ALAS1, HMGCS1, and VSIG4)." (PMID 30509175, 2018).
diabetes (3 papers, 2018 to 2023). "It is a process that goes through a high-affinity enzyme, AACS, that does not require a high AcAc concentration, and this process is probably more important in the fed state than in starvation or diabetes." (PMID 37356666, 2023).
hepatocellular carcinoma (2 papers, 2022 to 2025). A malignant tumor that arises from hepatocytes. "AACS, the key enzyme in ketone body utilization for lipid synthesis, is upregulated and implicated in the development and progression of hepatocellular carcinoma." (PMID 39554048, 2025). "As a category of ACS isozymes, members of ACS family (AACS, ACSF2-3, AASDH) participate in lipid metabolism; however, their expression patterns, regulatory mechanisms and effects in hepatocellular carcinoma (HCC) are poorly understood." (PMID 36205594, 2022).
liver fibrosis (1 paper, 2015). "These biomarkers are acetoacetyl-CoA synthetase (AACS), dipeptidyl-peptidase 4 (DPP4), d-dopachrome tautomerase (DDT), glutamine synthetase (GLUL), and glutathione S-transferase (GST); particularly, the plasma DPP4 and GST levels were highly associated with CCl4-induced liver fibrosis." (PMID 26491462, 2015).
infection (3 papers, 2016 to 2025). The state of being infected such as from the introduction of a foreign agent such as serum, vaccine, antigenic substance or organism. "At 8wks post infection, the most prominent genes which were significantly up-regulated in the liver tissue encode MCM, NDUF1, AACS, P450RAI-2, DARS, MRPL39, SOD1, associated with mitochondrial respiration and aerobic metabolism." (PMID 27467147, 2016). "Under the CDRV infection, the greatest up-regulated proteins (over 5 folds) were serum amyloid protein (U3IC83) and alpha-1-acid glycoprotein (U3I466); and the greatest down-regulated proteins were malic enzyme (U3IL38), fatty acid synthase (R0KBE2), and acetoacetyl-CoA synthetase (U3IQX8)." (PMID 29973707, 2018).
tumor (3 papers, 2015 to 2020). "Previous study indicated that acetoacetyl-CoA synthetase (AACS) was found in tumor tissues and plays important roles in metabolic processes of tumors." (PMID 25632391, 2015). "Our model predicts that Acetoacetyl-CoA Synthetase (AACS) depletion is selectively lethal to malignant cells because the alternative route for Acetoacetate-CoA synthesis, Acetyl-CoA Acetyltransferase 2 (ACAT2) is selectively depleted in the tumor region." (PMID 32103057, 2020).
cancer (2 papers, 2021 to 2025). A tumor composed of atypical neoplastic, often pleomorphic cells that invade other tissues. "We show that in cancer cells that can metabolize ketones, β-OHB-derived acetoacetate in the mitochondria can be shunted into the cytosol, where acetoacetyl-CoA synthetase (AACS) and thiolase convert it into cytosolic acetyl-CoA." (PMID 40921754, 2025).
neurological disorders (1 paper, 2022). "In literature, the data reveals that the ketone body is an fundamental element of cellular function and lipid metabolism, and exploration of transcriptional regulation of AACS could facilitate to clarify the role of ketone body utilization in neurological disorders." (PMID 36205594, 2022).
AACS also shares sentences with these, for which no sentence is quoted: Insulin resistance (2 papers); Alzheimer disease (1); breast carcinoma (1); cardiovascular disease (1); inflammation (1); Listeria infection (1); lupus (1); metabolic syndrome (1); thyroid cancer (1).